NRM (nurim)
Synonyms: NRM29
Tractability: Antibody: UniProt predicts a signal peptide or a membrane-spanning region. PROTAC: ubiquitination databases record sites on it.
Gene: Protein-coding gene on chromosome 6 (30,688,047 to 30,691,420, reverse strand). Ensembl gene ENSG00000137404.
Subcellular location: Nucleus inner membrane
Subcellular location (Human Protein Atlas): Nuclear membrane
Gene Ontology:
Molecular function: protein binding
Cellular component: membrane; nuclear envelope; nuclear membrane; nuclear inner membrane
Genetic constraint (gnomAD): Loss-of-function variants: 19 observed, 22.04 expected, observed/expected ratio (o/e) 0.86, 90% interval 0.6 to 1.26. The upper end of that interval is the gene's LOEUF score, 1.26, which puts it in group 5 of 6, group 1 being the genes least tolerant of losing a copy. Missense variants: 232 observed, 325.48 expected, observed/expected ratio (o/e) 0.71, 90% interval 0.64 to 0.8. Synonymous variants: 140 observed, 143.63 expected, observed/expected ratio (o/e) 0.97, 90% interval 0.85 to 1.12.
Homologues: Orthologues: chimpanzee NRM (99% identical), macaque NRM (98% identical), pig NRM (96% identical), dog NRM (95% identical), mouse Nrm (94% identical), rabbit NRM (93% identical), guinea pig NRM (69% identical), zebrafish nrm (50% identical), Drosophila melanogaster CG7655 (30% identical).
Diseases named in the same sentence as NRM in open-access papers:
NRM is named in the same sentence as 12 diseases in open-access papers, as found by Europe PMC text mining. Sharing a sentence is not in itself a finding about the gene and the disease. The quoted sentences say what the papers report.
asthma (1 paper, 2024). "Interestingly, a few genes such as NRM, PTPRE and SUZ12 were observed to be associated with Rheumatoid Arthritis, Asthma and Endometrial Stromal Sarcoma diseases, respectively, in humans and genes like SCNN1B associated with renal disease in cattle." (PMID 38674383, 2024).
axonal neuropathy (1 paper, 2007). Any nerve disorder affecting the axon of a nerve. "These include the NRM (nurim [nuclear envelope membrane protein]), ZDHHC19 (zinc finger, DHHC-type containing 19), UCP2 (uncoupling protein 2 [mitochondrial, proton carrier]) and GAN (giant axonal neuropathy [gigaxonin]) genes." (PMID 17974019, 2007).
colon cancer (1 paper, 2017). "This enabled us to analyze colon and rectal cases separately; as we only detected significant results for NRM expression, we may not have found significant results if we had combined colon and rectal cancers or examined only colon cancer cases." (PMID 28303484, 2017).
glioma (1 paper, 2024). A benign or malignant brain and spinal cord tumor that arises from glial cells (astrocytes, oligodendrocytes, ependymal cells). "A four-gene signature (ACTN1, AQP1, LAMC3, NRM) prognostic risk model was constructed among the differentially expressed genes (DEGs) identified in the grade II/III gliomas molecular subtypes." (PMID 38307919, 2024). "In this study, we constructed a novel and highly robust four-gene signature (ACTN1, AQP1, LAMC3, and NRM) based on EMT-related genes to predict grade II/III gliomas prognosis." (PMID 38307919, 2024). "Cellular experiments showed ACTN1, AQP1 and NRM promoted glioma cell proliferation, migration and invasion." (PMID 38307919, 2024). "Targeting the ACTN1, AQP1 and NRM genes may offer new therapeutic opportunities to improve grade II/III gliomas patient outcomes." (PMID 38307919, 2024).
myocardial ischemia (1 paper, 2024). A disorder of cardiac function caused by insufficient blood flow to the muscle tissue of the heart. "Genes like NRM, SLC6A6, and PTPRE are involved in Rheumatoid Arthritis, Myocardial Ischemia and Asthma diseases in humans." (PMID 38674383, 2024).
Parkinson disease (1 paper, 2022). A progressive degenerative disorder of the central nervous system characterized by loss of dopamine producing neurons in the substantia nigra and the presence of Lewy bodies in the substantia nigra and locus coeruleus. "‘NRM’, the third most important gene, the integral nuclear membrane protein Nurim, plays a role in the suppression of apoptosis, and apoptosis is the main mechanism of neuronal loss in Parkinson’s disease." (PMID 35627112, 2022).
cancer (1 paper, 2021). A tumor composed of atypical neoplastic, often pleomorphic cells that invade other tissues. "Its presence and prognosis in cancers have been less frequently evaluated; however, some studies suggest that the upregulation of NRM leads to decreased apoptosis along with enhanced cell migration and advanced cancer stage." (PMID 34888264, 2021).
NRM also shares sentences with these, for which no sentence is quoted: tumor (2 papers); cardiovascular diseases (1); rectal cancer (1); renal disease (1); rheumatoid arthritis (1).